EGFR (epidermal growth factor receptor)
Diseases named in the same sentence as EGFR in open-access papers (continued):
Sharing a sentence is not in itself a finding about the gene and the disease.
cancer (continued). "Furthermore, our results suggest a potential therapeutic use of AMPK agonists to target HER2 or EGFR signaling in cancer." (PMID 26143491, 2015). "Adding EGFR T790M-targeted immunotherapy to EGFR-TKI treatment could control the progression of cancer cells harboring T790M." (PMID 25532027, 2015). "Both EGFR inhibitor-sensitive and resistant cell lines overexpress cell proliferation genes, however the sensitive cell lines tend to overexpress apoptosis and cancer-related genes as well." (PMID 25948104, 2015). "Although KRAS mutations are associated with less efficient EGFR-directed targeted therapy in various cancer types, it is not yet known if the same is true in BTC." (PMID 26189560, 2015). "We next investigated whether CUDC-101 had any effect on cellular migration because ATC is a highly invasive cancer and the EGFR/RAS/BRAF/MEK/ERK pathway has been shown to regulate cellular migration and epithelial-mesenchymal transition (EMT)." (PMID 25940539, 2015). "This was a markedly improved prognosis when compared with the reported OS of approximately 14 months that was achieved in EGFR mutation-negative patients who received treatment with a cytotoxic anti-cancer agent." (PMID 26262682, 2015). "Mutations in EGFR and KRAS might be two different ways of conferring cancer phenotypes, but simultaneous mutations in both the genes might be non-optimal for cancer cell survival, and in this way, mutations in EGFR and KRAS are synthetic lethal." (PMID 26427375, 2015). "This could be relevant in view of the fact that many human cancers have elevated expression of EGFR along with Eph receptors." (PMID 25879388, 2015). "Knowing that EGFR's palmitoylation plays a critical role in its function, we sought to test whether inhibition of FASN or PATs activity can increase the sensitivity of cancer cells to EGFR tyrosine kinase inhibitors (EGFR TKI)." (PMID 26378037, 2015). "Ligand-activated GPER triggers the rapid activation of transduction pathways such as epidermal growth factor receptor (EGFR) and mitogen-activated protein kinases (MAPKs), leading to a specific gene signature and the migration and proliferation of cancer cells and CAFs." (PMID 26183213, 2015). "In addition, the blockage of EGFR results in a significant growth inhibition of several cancer cell lines derived from human carcinomas." (PMID 26491668, 2015). "This cross-reactivity seems to be favorable for efficacy against EGFR T790M+ cancer cells." (PMID 25532027, 2015). "This response occurs in a biphasic manner as secondary activation of the EGFR is observed followed initial radiation-induced activation in cancer cells and may be mediated by radiation-induced cleavage and autocrine action of TGFα." (PMID 26546517, 2015). "Thus, the up-regulated members of these compensatory pathways along with the members of the EGFR/ErbB signaling pathway are interesting as potential targets for designing novel anti-cancer therapeutics." (PMID 25599599, 2015). "In addition, potent multivalent nanobodies can be produced and can bind a number of targets, allowing to design multivalent agents that combine several modes of EGFR or other cancer target inhibition." (PMID 26635612, 2015). "This might be due to the abundant levels of EGFR that the MDA-MB-231 cells express as a result of being a more metastatically aggressive cancer cell line." (PMID 26493292, 2015). "Similar to HER-3, EGFR is expressed in cancer but also in normal epithelial cells." (PMID 26538233, 2015). "Mutations in the tyrosine kinase domain of EGFR that are known to associate with response or resistance to EGFR therapy in other cancers are rare in patients with HNSCC and do not correlate with efficacy of EGFR-inhibition or clinical outcome." (PMID 25823819, 2015). "Furthermore, mutation of EGFR at Y1045 attenuated WJ-induced cell growth inhibition as well as its anti-cancer effect and EGFR degradation in vivo, suggesting the important role of EGFR in EGFR wt NSCLC." (PMID 25980579, 2015).
cancer (continued). "Deregulation of the EGFR phosphorylation contributes to cancer." (PMID 25970784, 2015). "These cumulative results suggest that targeting STAT3 may overcome the resistance to EGFR-TKI in cancer cells." (PMID 26542452, 2015). "In conclusion, the overexpression of NEU3 could cause the constitutive activation of EGFR together with Src activation in the presence of EGF, and subsequently potentiation of the tumorigenicity of cancer cells." (PMID 25803810, 2015). "Cancer cells with acquired cisplatin resistance were shown to express higher levels of EGFR, compared to their parental cell lines, and were more dependent on EGFR signaling." (PMID 26568478, 2015). "GPCR and EGFR/ErbB over-expression often contributes to cancer growth." (PMID 25599599, 2015). "These properties render EGFR an attractive target for cancer therapy." (PMID 25885222, 2015). "Further studies that could evaluate co-localization and activity of cofilin-1 and EGFR in cancer cells would help to elucidate how exactly they are working together towards resistance behavior against cisplatin treatment." (PMID 25784483, 2015). "Epidermal growth factor receptor (EGFR) plays a crucial role in cancer cell proliferation." (PMID 26305257, 2015). "Indeed, EGF-like peptides and angiogenic growth factors that can both act on endothelial cells and activate EGFR in cancer cells are produced by bone marrow stromal cells." (PMID 26635612, 2015). "In addition, this case showed carcinoma-specific amplification of 7p (EGFR and BRAF) and 20q (ASXL1, AURKA, and GNAS), which were observed as clonal amplification for the three MSS cases without ERBB2 amplification." (PMID 26336987, 2015). "In addition to this action, recent evidence indicates that EMT changes develop a resistance to a several anti-cancer agents such as EGFR-tyrosine kinase inhibitor, cisplatin, gemcitabine, and 5-FU." (PMID 25140293, 2014). "Moreover, cancers with MT K-Ras are more aggressive and resistant to targeted therapies such as anti-EGFR (epidermal growth factor receptor) and MAPK kinase (MEK) inhibitors." (PMID 24962213, 2014). "The EGFR pathway is frequently dysregulated in human cancer and it was proposed that activation of EGFR may regulate the immunological visibility of stressed premalignant cells." (PMID 24860567, 2014). "Interestingly, HNSCCs show the highest frequency of high EGFR expression levels among all different types of cancers, and hence EGFR-targeted therapies are expected to exhibit beneficial effects." (PMID 24621372, 2014). "EGFR overactivity may lead to sustained signals for anti-apoptosis, cell proliferation, angiogenesis and metastasis, the basic properties of cancer." (PMID 24658383, 2014). "Based on the clinical significance of EGFR and Fascin, we hypothesized that a combination of molecules from the EGFR/ERK/Fascin signaling pathway could accurately predict cancer outcome." (PMID 25153136, 2014). "Based on the EGFR/VEGF target in the treatment of cancer is the hot spot in drug research." (PMID 23943374, 2014). "However, cancer cells always have many signal channel ways to reproduce, and EGFR and IGFR are only two of these ways." (PMID 24618737, 2014). "EGFR inhibitors, drugs targeting the intracellular kinase activity and antibodies targeting the extracellular ligand binding, are used to treat breast, lung, colon and other cancers." (PMID 25184905, 2014). "Furthermore, HTEIs targeting SR-BI or EGFR have been shown to have an acceptable clinical safety profile in inflammatory disease and cancer." (PMID 24830295, 2014).
cancer (continued). "Structural determination of the EGFR wild-type kinase and cancer mutants in complexes with inhibitors and interacting proteins has recently produced molecular insights into the functional effects of protein flexibility and relevant genetic modifications of this flexibility." (PMID 24817905, 2014). "This review addresses the regulation of EGFR endocytic trafficking and the consequences of this regulation for the spatiotemporal control of signaling and cell fate in normal conditions, as well as in tumorigenesis and the response to cancer therapy." (PMID 24295852, 2014). "Epidermal growth factor (EGF) and their receptor (EGFR) play an important role in the development of cancer proliferation, and metastasis, although the mechanism remains unclear." (PMID 24268047, 2014). "EGFR-based therapy has been used in the treatment of these cancers with variable success." (PMID 25158139, 2014). "These alternative pathways may bypass or evade inhibition of EGFR signaling, thereby enabling combinations of agents to simultaneously attack multiple molecular targets for cancer growth inhibition." (PMID 24939055, 2014). "However, other combinations include sensitizing cancer cells with anti-angiogenic factors, EGFR blockade or Cox-2 inhibitors, among others." (PMID 25379013, 2014). "The EGFR signaling pathway activates diverse cellular targets which are crucial for cell proliferation, survival, angiogenesis, migration and adhesion and are often dysregulated in cancer cells." (PMID 24811863, 2014). "The chemical synthesis of other GM3 derivatives using approaches similar to those described in the present study, has the potential to create more potent EGFR inhibitors to block cell growth or motility of a variety of types of cancer that express either wild-type EGFR or ΔEGFR." (PMID 24944646, 2014). "STAT3 is critically involved in EGFR-induced cancer cell migration and invasion." (PMID 24662938, 2014). "Based on VAV3 expression levels and the response to erlotinib in cancer cell lines, targeting EGFR signaling may be a promising therapeutic strategy." (PMID 24886537, 2014). "However, it has been reported, an increase of 50–90% in epidermal growth factor receptor (EGFR) expression in RCC, being this up-regulation associated with higher cancer grade and worse prognosis." (PMID 25909813, 2014). "However, in human cancer cells, EGFR-L858R is down-regulated, but their assessment of ubiquitylation and CBL binding were markedly different." (PMID 25594057, 2014). "EGFR signalling regulates cell proliferation, cell differentiation, cell cycle, and cell migration and therefore it has been a potential interested target for effective cancer therapies." (PMID 25080090, 2014). "Moreover, “EGFR-addicted” cancer cell lines induced to undergo EMT become erlotinib-resistant in vitro." (PMID 25193862, 2014). "In addition to the traditional pathways of EGFR signaling, EGFR translocates to the nucleus and acts as a transcription factor in the proliferation of cancer cells." (PMID 25416285, 2014). "Moreover, EGFR has been found to regulate the capacity of stemness in cancer cells through AKT and ERK signaling." (PMID 25003232, 2014). "EGFR is a ~170 kDa glycoprotein that regulates stem-like properties in many types of cancers." (PMID 25003232, 2014). "Cezanne-1 deubiquitinates and stabilizes EGFR, enhancing EGFR signaling and cancer progression." (PMID 25121098, 2014). "Clinical trial records should now be stratified to determine whether the efficacy of EGFR-inhibitory regimes correlates with platelet counts in cancer patients." (PMID 25210793, 2014). "Furthermore, treatment of cancer cells with EGFR inhibitors such as afatinib and dacomitinib can activate the IL-6/JAK/STAT3 signaling pathway, which in turn induces resistance to these agents." (PMID 24662938, 2014).
cancer (continued). "Judicial use of EGFR-targeting combinations, i.e., simultaneous use of antibodies and multiple kinase inhibitors, may provide more effective cancer treatments with fewer side-effects and avoid development of resistance." (PMID 25184905, 2014). "However, combined treatment of CX-4945 and EGFR-TKI effectively inhibited cancer-cell proliferation and induced apoptosis." (PMID 25486409, 2014). "A comparatively new and exciting area is the additional role that EGFR activation and traffic may play in regulating responses to cancer therapy." (PMID 24295852, 2014). "Finally, as the EGFR pathway is frequently activated in cancers and can activate both mTOR and Mnk1, we treated cells with the EGFR inhibitor erlotinib." (PMID 24884945, 2014). "EGFR signaling was also important for eHsp90’s pro-motility function in a number of cancer models." (PMID 24805867, 2014). "However, as cancer cells quickly adapt and become resistant to Cetuximab therapy, combination therapies that would be tailored to individual patients are proposed as a novel strategy for the treatment of EGFR-driven cancers." (PMID 25520666, 2014). "Anti-EGFR drug is currently being tested in clinical trials using cancer patients." (PMID 25594013, 2014). "Moreover, enhanced EGFR signaling activity was reported to contribute to cancer progression from various origins through the elevation of cancer cell survival, proliferation, and migration." (PMID 24906407, 2014). "Cetuximab, an anti-EGFR monoclonal antibody, is used to treat several cancers." (PMID 25344208, 2014). "Altering Notch signaling might lead to the differentiation of cancer cells, while targets such as EGFR or PI3K target cell proliferation only." (PMID 25601901, 2014). "Heregulin expression was weak-to-absent in stromal cells, including fibroblasts, but was nearly absent in glandular epithelial cells of colorectal mucosa adjoining cancer tissue.EGFR immunoreactivity was observed in cancer cells in 79 cases (51%; 40% with score 2+ and 10% with score 3+)." (PMID 25416285, 2014). "Targeting TGF-β and prostaglandin E2 may allow for improved outcomes for cancer patients treated with combination immunotherapy and EGFR inhibitors." (PMID 25240937, 2014). "In addition to Ras and EGFR, several microRNAs (miRs) have been shown to influence cancer development." (PMID 25004126, 2014). "Although the ranking is low among other EGFR mutations, the priority score is 0.6178, indicating that it is predicted as more likely than not to be cancer-associated." (PMID 24743239, 2014). "Moreover, as the pool of cancer stem cells also critically relies on KIAA1199, our data thus define KIAA1199 as a promising target to interfere with deregulated EGFR signalling in cancer." (PMID 25366117, 2014). "To date, EGFR is one of the most successful rational drug targets in clinical cancer therapy." (PMID 24801752, 2014). "Based on the observation that PI4KIIα knockdown reduced EGFR protein levels, we asked whether dual control of protein level and activity of EGFR results in enhanced effects during anti-cancer therapy." (PMID 24801752, 2014). "Our studies identify T725M and L861R as rare cancer-associated mutations inasmuch as these mutations increase EGFR activity in the absence of the activating EGF ligand in cell-based assays." (PMID 24743239, 2014). "Therefore, targeting EGFR has been intensely pursued over the last three decades as a cancer treatment strategy." (PMID 25344208, 2014). "To illustrate this, we have extracted the I/O response RDSP of the PI3K/PTEN/AKT and MAPK pathways for different cancer cell lines using experimental data on the dose dependence of receptor activation (EGFR and PDGFR) and output signal (pAKT and pERK) on ligand concentrations (EGF and PDGF)." (PMID 24551596, 2014).
cancer (continued). "We were particularly interested in EGFR because of its positive roles in cancer cell invasion." (PMID 24816687, 2014). "Although propofol induces apoptosis and inhibits the invasion of cancer cells both in vitro and in vivo via different molecular mechanisms, we focused on the anti-cancer properties of propofol that are regulated via EGFR signaling pathway." (PMID 25502773, 2014). "In addition to the traditional pathways of EGFR signaling, several studies have reported that EGFR translocates to the nucleus and acts as a transcription factor in the proliferation of normal and cancer cells alike." (PMID 25416285, 2014). "The role of EGFR:rs2227983 (G to A, R497K) in cancer has been extensively investigated." (PMID 24945674, 2014). "In this study, we showed that B4GALNT3 regulates cancer cell property via EGFR pathway." (PMID 25003232, 2014). "Furthermore, RNAi experiments targeting EGFR demonstrated cancer growth suppression in A549 xenograft in mice." (PMID 24961498, 2014). "Anti-EGFR mAb:s are suggested to exert their anti-cancer effects by blocking these pathways." (PMID 24940619, 2014). "While both EGFR and Na,K-ATPase seem to modulate similar signaling pathways, cardiac glycosides that are steroid-like inhibitors of Na,K-ATPase, exhibit antiproliferative and proapoptotic properties in cancer cells." (PMID 25052069, 2014). "To identify potential therapeutic vulnerabilities specifically within these mesenchymal, erlotinib-resistant cells, we performed a small molecule screen of ~200 established anti-cancer agents using the EGFR mutant NSCLC HCC827 cell line and a corresponding mesenchymal derivative line." (PMID 25193862, 2014). "Accordingly, treatment of cancer cells with anti-MUC1 antibody inhibits EGFR signaling." (PMID 25499743, 2014). "Rare MET-amplified cells have been found also in CRC tissue samples before anti-EGFR treatment, suggesting that EGFR-targeted therapies may act as a selective pressure to expand a preexisting subclonal population of cancer cells harboring MET amplification." (PMID 28548075, 2014). "Our study provides evidence that combination therapy with metformin and erlotinib could have therapeutic efficacy in cancers driven by EGFR and PI3K signaling, including a subset of BBC patients, and provides a rationale for clinical study." (PMID 25361177, 2014). "In addition, MET also contributes to cancer resistance against EGFR inhibitors through bypass signaling." (PMID 24500024, 2014). "Taken together, SOX2 mediates self-renewal of CSCs through EGFR signaling in at least two cancer types and is a major mediator of self-renewal in several cancers through mechanisms that remain unclear." (PMID 25114775, 2014). "Aberrant activation of EGFR in various tumors regulates cancer stem cell properties." (PMID 25003232, 2014). "Thus, we examined the sensitivity of DF in combination with the EGFR/ERBB2-targeting reagent lapatinib on cancer cells." (PMID 24587811, 2014). "Expression of EGFR and of their ligands has been demonstrated to occur with high frequency in a majority of human carcinomas, and therefore might play an important role in the pathogenesis of these diseases." (PMID 24709893, 2014). "However, positive staining of EGFR and Fascin was apparent only in basal layer of epithelium tissue adjacent to carcinoma, while p-Sp1 was weak staining in higher granular layer of the epithelium." (PMID 25153136, 2014). "It is now widely accepted that EGFR transactivation in response to the stimulation of GPCRs occurs in a large number of cancer cells, and it is believed that this mechanism is an important signalling principle contributing to cancer development and progression." (PMID 24215724, 2013). "Furthermore, in HeLa cancer cells, a well-known model for studying the EGFR receptor function, Shh also induces cell proliferation involving EGFR activation, as reflected by EGFR internalization and ERK1/2 phosphorylation." (PMID 24133411, 2013).